TLR3 (toll like receptor 3)
Diseases named in the same sentence as TLR3 in open-access papers (continued):
Sharing a sentence is not in itself a finding about the gene and the disease.
cancer (continued). "The data presented here clearly demonstrate that the clinical potential associated with TLR3 activation is not restricted to the adult population but could also be a promising avenue for the treatment of children and adolescent’s cancers." (PMID 37414800, 2023). "However, TLR3 activation have also been reported to promote cancer progression." (PMID 35413927, 2022). "Interestingly, there is growing evidence that TLR3 is also generated in cancer cells, and the generation of TLR3 in cancer cells may exert an opposite effect in different cancer progression." (PMID 36419829, 2022). "Likewise, TLR3 possesses multifaceted functions in cancer regulation." (PMID 35000541, 2022). "Therefore, we investigated TLR3 expression in different cancers and its effect on cancer prognosis." (PMID 36419829, 2022). "Indeed, anthracyclines, such as viruses, lead to cancer cell-autonomous, TLR3-mediated, Type I IFN production, that triggers autocrine and paracrine IFNAR-dependent circuits, finally resulting in the expression of various ISGs, including CXCL10 (known to recruit innate immune cells)." (PMID 34571733, 2021). "Alternatively, transgenic mice (e.g., Ifnar−/−, Tlr3−/−, among the others) could be either implanted with Wt cancer cells or treated with carcinogens or genetically engineered to develop spontaneous tumors to study Type I IFN signaling on immune and even stromal cells." (PMID 34571733, 2021). "This may be the reason why in different cancers, the effects of TLR3 can be varied." (PMID 33986756, 2021). "Whether this dual behavior can be related to cancer type or individual characteristics, it is useful to closely monitor the outcome of chemotherapies in patients in terms of TLR3 expression and response to better understand the role of the receptor in each particular case." (PMID 33147700, 2020). "Given the up-regulation of TLR3 in most cancer types and given the ability of this receptor to trigger apoptosis, together with its capacity to activate the immune system cells, TLR3 might be considered as an important therapeutic target for the treatment of cancer." (PMID 33147700, 2020). "However, a proportion of TLR3-expressing cancer cell lines, including NSCLC, remain resistant to TLR3-mediated apoptosis, and the underlying mechanism of resistance remains unclear." (PMID 30158588, 2018). "TLR3 activation may regress cancers by inducing apoptosis and inhibiting cell proliferation." (PMID 28427199, 2017). "Thus, cancer cells respond to various anthracyclines by activating a TLR3-elicited signal transduction cascade resulting in type I IFN release, autocrine/paracrine type I IFN signaling, and chemokine (C–X–C motif) ligand 10 (CXCL10) secretion, two phenomena that underlie their vaccinating potential." (PMID 25964783, 2015). "Various synthetic TLR3 agonists are available and some of them, including polyinosinic:polycytidylic acid (polyI:C) and its clinical grade analog polyI:polyC12U (also known as rintatolimod and AmpligenTM), have been extensively tested as immunostimulants in cancer patients." (PMID 25964783, 2015). "An invasion assay indicated that TLR3 knockout significantly reduced the invasive properties of the cancer cells, while rescue with NLS-TLR3 led to a more invasive phenotype compared to NES-TLR3." (PMID 40675966, 2025). "Consequently, the actions of TLR3 that improve prognosis in cancer patients remain unclear." (PMID 40029556, 2025). "In the present study, we observed both direct induction of apoptosis in TLR3-expressing cancer cells and strongly enhanced secretion of CXCL10 from cancer cells." (PMID 40029556, 2025). "The nuclear TLR3 is found to be able to recruit the arginine methyltransferase PRMT5 to promote symmetrical dimethylation and multimerization of c-Myc in cancer cells." (PMID 40675966, 2025). "CD133 co-localized with TLR3 in all cells and was expressed in all tested HNSCC cancer tissue (PCC retromolaris, gingiva mandibulae, gingiva maxillae, and linguae)." (PMID 40647457, 2025).
cancer (continued). "To investigate the role of nuclear TLR3 of cancer cells, we rescued TLR3 knockout Panc1 cells by expressing wild-type TLR3, the TLR3 with a nuclear localization signal (NLS-TLR3), or the TLR3 with a nuclear export signal (NES-TLR3)." (PMID 40675966, 2025). "We verified the interaction between TLR3 and PRMT5 in the nucleus of Panc1 and A549 cancer cells upon chemotherapeutic stress by immunoprecipitation and immunofluorescence." (PMID 40675966, 2025). "RAGE was strongly expressed in the gingiva maxillae throughout the cancer tissue; however, in other tested tissues, RAGE was expressed in some cells where it co-localized strongly with TLR3." (PMID 40647457, 2025). "For example, when the cancer vaccine NY-ESO-1 is combined with the TLR3 agonist poly-ICLC, the immune response against the cancer/testis antigen NY-ESO-1 is enhanced." (PMID 38370407, 2024). "Herein, we identify TLR3/4-TBK1-IRF3 signaling as the critical regulator of IL-33 expression and discover statin to suppress IL-33 expression by regulating TBK1 signaling in cancer-prone chronic inflammation." (PMID 38816352, 2024). "As exhibited in different cancer model systems, MYD88 directs innate immune signalling through the TLR members (except TLR3) and the IL-1 family and can function doubly in pro- and anti-tumorigenic responses." (PMID 38256152, 2024). "On the one hand, the TLR3 signal sequentially activated IRF3 and NF‐κB after poly I:C (a TLR3 agonist) stimulation, which resulted in the release of IL‐6 and C‐C motif chemokine ligand 5(CCL5), as well as the enhancement of cancer cell migration." (PMID 38685971, 2024). "For example, TLR3 and TLR7 agonists activated NF-κB and triggered secretion of immune-stimulatory cytokines in macrophages and have been in clinical trials for cancer therapy." (PMID 38646639, 2024). "They showed that 10 Gy irradiation of cancer cell lines (U2OS, A549, HEPG2 and MCF7) increased the expression of TLR2, TLR3, TLR4, TLR6 and TLR9." (PMID 37112730, 2023). "TLR3 and TLR10 were found to be significant in nine malignancies, while TLR4 was shown to be significant in eight cancers." (PMID 35801728, 2022). "Majority of the NRGs were deregulated in cancer tissues as compared to normal tissues which showed a uniform downregulated expression pattern except for NDRG2, BCL2, PRKN, TLR3, and STUB1." (PMID 36389725, 2022). "In comparison, FADD in 12 cancer types, FASLG in 3 cancer types, RIPK1 in 19 cancer types, TLR3 in 25 cancer types, TNF in 11 cancer types, FAS in 22 cancer types, MLKL in 15 cancer types, and RIPK3 in 12 cancer types had homozygous deletions." (PMID 35748782, 2022). "TLR1, TLR2, TLR3, TLR4, and TLR5 expression levels were high across the six immune subtypes in the pan-cancer data; TLR6, TLR7, TLR8, and TLR10 expression levels were moderate; and TLR9, TLR12P, and TLR8-AS1 expression levels were extremely low." (PMID 35801728, 2022). "For the immune score, expression of TLRs was positively correlated with immune scores in almost all types of cancer, except TLR1 in UVM, TLR3, 4, and 5 in THYM, and TLR10 in DLBC." (PMID 35937402, 2022). "To promote the clinical transformation of the NRGs signature, we further identified the sensitive FDA-approved drugs for multiple cancer cell types with higher expressions of FASLG, TLR3, and ZBP1." (PMID 35165523, 2022). "The overexpression of StAR has been shown to affect toll-like receptor 3 (TLR3), TLR6, and lymphotoxin alpha (LTα) activities, which contribute to various cancers." (PMID 35740335, 2022). "TLR agonists approved by the FDA for the treatment in cancer patients include Bacillus Calmette-Guérin (BCG) (activates TLR2, TLR3, TLR4 and TLR9), monophosphoryl lipid (MPL) (TLR4 agonist) and imiquimod (TLR7 agonist)." (PMID 36365103, 2022). "Treatment of cancer cells with DNA methyltransferase inhibitors (DNMTis) activates RNA sensors, including MDA5 and the endosomal dsRNA sensor Toll‐like receptor 3 (TLR3)." (PMID 35156720, 2022).
cancer (continued). "This is consistent with previous studies where treatment of cancer cells with DNMT inhibitors led to overexpression of ERV, which triggered the activation of the double-stranded RNA sensor TLR3 and, in turn, a type I interferon response." (PMID 34272378, 2021). "Modified TLR3 agonists (Ampligen®, Hiltonol®, poly ICLC) are already being used in clinical studies for cancer therapy as single agents or in combination with other drugs." (PMID 33503958, 2021). "The TLR3 agonist Poly(I:C) induced the expression of the IRF3 target genes IFNB and CXCL10 in all tested cancer cell lines suggesting that defects upstream of TBK1/IKKe render the cancer cells unresponsive to STING agonists." (PMID 33790360, 2021). "Indeed, Takeda and colleagues used a cancer vaccine, containing a tumor-associated antigen (TAA) to ARNAX, for the treatment of murine T cell lymphoma by subcutaneous injection, thus inducing CD8+ T cell priming through activation of the TLR3-TICAM-1-IRF3-IFN-β pathway in DCs." (PMID 33147700, 2020). "The mechanism of the antitumorigenic effect of TLR3 is well-established, wherein the TRIF-dependent classical pathway induces apoptosis in cancer cells through the endosomal compartment." (PMID 33072559, 2020). "Specifically, cancer nano-vaccines co-deliver peptides and TLR9 agonists, and gold nanoparticles the anionic TLR3 agonist poly I:C co-delivered with cationic antigen peptides." (PMID 33679703, 2020). "TLR3 activation induced the expression of the axon guidance gene SLIT2 in endothelial cells, which mediated the migration of cancer cells to endothelial cells for intravasation, which was dependent on ROBO1, a SLIT2 receptor." (PMID 33633744, 2020). "To demonstrate the mechanisms through which cancer cells sense cytosolic Poly(I:C) and Poly(dA:dT), we first examined the activation and expression of PKR, TLR3, RIG-I, MDA5, LGP2, and DHX29 stimulated by Poly(I:C) and Poly(dA:dT) in PANC-1 cells." (PMID 33490069, 2020). "Apart from TLR4, other TLRs as TLR2, TLR3, and TLR9 were already shown, in preceding cancer, hepatic cirrhosis." (PMID 30976817, 2019). "When considering treatment of patients suffering from PSCA-positive cancers with anti-PSCA-RICIA, it can be predicted that tumorigenic as well as normal cells expressing PSCA at sufficient surface levels and containing TLR3 are affected by anti-PSCA-RICIA." (PMID 30824859, 2019). "Toll-like receptor 3 (TLR3) mediates innate immune responses by sensing viral dsRNA, but also induces apoptosis selectively in cancer cells." (PMID 30158588, 2018). "EGFR-mediated entry of HIV-positive exosomes into target cancer cells is a necessary step for subsequent activation of ERK1/2, a process that involves EGFR and TLR3." (PMID 30389917, 2018). "TLR3 activation induces inflammatory cytokines but also induces type I IFN production, which impairs proliferation and induces apoptosis in some cancer cells (9, –, 11)." (PMID 28717003, 2017). "Thus, TLR3 signaling is multifaceted and may have opposing effects on cancer progression." (PMID 28717003, 2017). "Synthetic TLR3, TLR4, TLR7, and TLR9 ligands are being tested in cancer patients as single agent or in combination with cancer vaccines and ligands for other TLRs are in development." (PMID 28003994, 2016). "The availability of clinical grade TLR3 agonists, recombinant type I IFNs, and pre-clinical recombinant CXCL10 provide promising avenues for targeted cancer therapies." (PMID 26486085, 2015). "Clinical studies assessing the prognostic and predictive value of TLR3 status and type I IFN signaling in cancer patients." (PMID 26300886, 2015).
cancer (continued). "Their study demonstrated that the expression of toll-like receptor 3 (TLR3) in HCC cells positively correlated with hepatitis B virus (HBV) infection, interstitial immunoreactive cells infiltration, and cancer cell apoptosis." (PMID 26064094, 2015). "The potential use of the immunostimulatory properties of TLR agonists, particularly TLR2, TLR3, TLR4, TLR7/8, and TLR9, has been investigated in cancer immunotherapy." (PMID 25309546, 2014). "Laser capture microdissection revealed an increase in TLR3 and a decrease in TLR1 mRNA levels in dysplastic and carcinoma epithelium, respectively." (PMID 22013487, 2012). "Synthetic agonists for several TLRs, including TLR3, TLR4, TLR7, TLR8, and TLR9, have been or are being developed for cancer treatment." (PMID 21861882, 2011). "In this review, we provide a comprehensive and mechanistic analysis of TLR3 signaling in epithelial cancers, encompassing canonical and non-canonical modules that regulate cancer cell fate." (PMID 42278599, 2026). "Additionally, ongoing trials are evaluating Rintatolimod as a therapy for COVID-19 in cancer patients (NCT04379518) and post-COVID fatigue (NCT05592418), further expanding the clinical applications of this TLR3 agonist." (PMID 39988665, 2025). "Here, the authors show that TLR3/4-TBK1-IRF3 pathway activation induces IL-33, and the cholesterol-lowering drug, statin, blocks this pathway to suppress chronic inflammation and its cancer sequela." (PMID 38816352, 2024). "A logistic regression model, using 5 proteins (ITGB5, TGF-α, TLR3, WIF-1, and ERBB3) with highest AUC values, demonstrated good predictive performance for prognosis of CC patients undergoing immunotherapy and showed potential across different cancer types." (PMID 38835778, 2024). "TLR3 acts also as a death receptor only in cancer cells but not in their normal counterparts, making it an attractive target for cancer therapies." (PMID 37275475, 2023). "Epigenetic remodeling in the cancer landscape can lead to mobilization of the TEs which are also ligands of innate immunity particularly of RNA via TLR3, RIG1, and MDA5 receptors, of DNA via TLR3/7/8, and cGAS." (PMID 37854446, 2023). "In addition to TLR3, TLR7 agonists also inhibit Treg cell function, and activate NK cells, promoting anti-cancer immune responses." (PMID 37936697, 2023). "To date, no TLR3 agonists have reached market approval in the treatment of cancer due to systemic toxicity, limited efficacy, lack of structural homogeneity, and most importantly lack of TLR3 specificity." (PMID 37275475, 2023). "Survival analysis showed that CNVs of TNF in 22 cancer types, TLR3 in 10 cancer types, RIPK1 in 9 cancer types, FAS in 8 cancer types, FADD in 8 cancer types, RIPK3 in 7 cancer types, MLKL in 6 cancer types, and FASLG in 5 cancer types were significantly associated with overall prognosis." (PMID 35748782, 2022). "In addition, for the stromal scores, the expression of TLRs was positively correlated with stromal scores in almost all types of cancer, except TLR1 in UVM and TLR3 in ACC, LAML, MESO, and READ." (PMID 35937402, 2022). "Meanwhile, homozygous CNV analysis showed that FADD in 22 cancer types, FASLG in 25 cancer types, RIPK1 in 22 cancer types, TLR3 in 15 cancer types, TNF in 23 cancer types, FAS in 15 cancer types, MLKL in 12 cancer types, and RIPK3 in 17 cancer types had homozygous amplifications." (PMID 35748782, 2022). "TLR3 was not up-regulated in any of the cancer tissues tested, whereas TLR1 was inversely up-regulated only in KIRC (P0.01), CHOL (P0.05), and GBM (P0.001)." (PMID 35801728, 2022). "Tavora et al23 reported that TLR3 could induce the expression of SLIT2 and promote cancer progression." (PMID 33783985, 2021).
cancer (continued). "Although RIG-I is expressed in most cell types, TLR-3 and TLR-7 expression is restricted to DCs and other antigen-presenting cells that are present in the TME and are believed to play a critical role in the recognition of cancer by the immune system." (PMID 32088771, 2020). "The resulting heatmap showed that in the majority of malignancies, TILs were significantly correlated with multiple representative ICD mediators, such as CALR, LRP1, ANXA1, FPR1, TLR3, IFNAR1, PANX1, and P2RX7." (PMID 33299118, 2020). "Therefore, we systematically analyzed the expression, molecular cascade, and functions of TLR3, RIG-I, MDA5, LGP2, cGAS, and STING in human cancer cells." (PMID 33490069, 2020). "There is no clear correlation between TLR3-dependent prognosis and cancer type or intracellular localization of the receptor." (PMID 33147700, 2020). "The prognostic value of TLR3 in cancer is debated and no data are currently available in NSCLC, for which therapeutic approaches that target the immune system are providing encouraging results." (PMID 31582772, 2019). "We then addressed the sensitivity to the paclitaxel/poly(I:C) combination of the non-transformed HBECT-3KT cells which are, in contrast to cancer cells, efficiently protected against TLR3-mediated apoptosis via a cIAPs/c-FLIP double brake." (PMID 30158588, 2018). "In agreement, in H400 cancer cells that can be sensitized to Poly(I:C)-triggered apoptosis when the c-FLIP, but not cIAPs, brake only is released, paclitaxel also reduced the expression of c-FLIP, and sensitized these cells to TLR3-mediated death." (PMID 30158588, 2018). "In contrast to cancer cells, non-transformed airway epithelial cells appear to be resistant to TLR3-induced apoptosis in vitro." (PMID 30158588, 2018). "Remarkably, the release of the c-FLIP brake only results in the sensitization of 8/8 human cancer cell lines but not normal cells to TLR3-mediated apoptosis." (PMID 30158588, 2018). "Combination of polyI:C and anti-IL6 antibody enhanced polyI:C-suppressions of survival, oncogenicity, and metastasis of A549 and potentially other cancer cells, as long as they express sufficient but non-saturating levels of functional TLR3 protein." (PMID 28427199, 2017). "Previous studies using a rat model showed that activated TLR3 could inhibit HCC development and progression by inhibiting cell invasion and inducing apoptosis in cancer cells." (PMID 28127569, 2017). "While TLR3 levels were found to be significantly higher in dysplastic epithelial samples (P = 0.05, Student's t-test), TLR1 levels were found to be significantly lower in carcinoma epithelium (P = 0.01, Student's t-test)." (PMID 22013487, 2012). "In undifferentiated G3 carcinoma, staining for TLR3 and TLR4 was not detectable, strengthening our findings of low TLR3 and TLR4 mRNA abundance in G3 carcinoma." (PMID 18775079, 2008). "Here, we report that TLR3 in cancer cells undergoes nuclear translocation under chemotherapeutic stress and acts as an oncogenic protein to recruit arginine methyltransferase PRMT5 to promote dimethylation and multimerization of c-Myc, consequently facilitating cancer metastasis and chemoresistance." (PMID 40675966, 2025). "In summary, we observed that TLR3 is highly expressed in ESCC lines and that its activation strongly induces expression of CXCL10, which is a major mediator of an antitumor immune response that may improve prognosis in cancer patients." (PMID 40029556, 2025). "Therefore, it is important to keep in mind that no external ligands are necessary for TLR3 stimulation and its potential contribution to cancer progression." (PMID 37894949, 2023).